IFITM1 (interferon induced transmembrane protein 1)
Diseases named in the same sentence as IFITM1 in open-access papers (continued):
Sharing a sentence is not in itself a finding about the gene and the disease.
cancer (52 papers, 2007 to 2026). A tumor composed of atypical neoplastic, often pleomorphic cells that invade other tissues. "Interferon-induced transmembrane protein 1 belongs to a group of IFITM proteins that have been implicated in cancer aggressiveness and chemoresistance." (PMID 39336161, 2024). "Cancer cell 2 expressed Sprr1a, Lgals7, and Ifitm1, which are associated with the mesenchymal/basal-like subtype and a poor prognosis in PDAC." (PMID 37998349, 2023). "This indicates that IFITM1/3 can regulate the synthesis of some antivirals in addition to cancer-associated gene products." (PMID 36008984, 2022). "Therefore, the variable nature of association of IFITM1 with cancer prognosis suggests that it should be carefully approached to utilize IFITM1 as a biomarker." (PMID 27852071, 2016). "While interferon-induced transmembrane proteins (IFITM1/2/3) are established in viral defense and cancer progression, their roles in cardiovascular pathologies are undefined." (PMID 41368318, 2025). "The nine genes identified in our signature (Dhx9, Dusp12, Fhl1, Ifitm1, Ndufs1, Pja2, Slc1a3, Soga1, and Spon2) have each been investigated for their role in cancer." (PMID 38193115, 2024). "IFIT1 affects cancer cell behavior through Wnt/β-Catenin signaling, and IFITM1, IFITM2, and IFITM3 are related to antiviral functions." (PMID 38424218, 2024). "We next examined how overexpression of WT ENPP1 in cancer cells affected STING activation in cGAMP responder cells as measured by their combined Ifitm1, Ifitm2, and Ifitm3 expression (Ifitms)." (PMID 38117852, 2023). "In the context of cancer, KO of IFITM1/3 impairs the protein synthesis of a group of molecules induced by IFNγ including HLA-B and ISG15." (PMID 36435199, 2023). "Previous studies have indicated that IFITM1 is an independent prognostic marker for cancer patients." (PMID 36591519, 2022). "A total of 301 IRGs were identified from the GSE32571 dataset, and IFITM1 was a down-regulated gene in several types of cancer, including PRAD." (PMID 36591519, 2022). "IFITM1/2/3 are IFN-stimulated molecules involved in human cancer development, including cervical carcinogenesis." (PMID 36008984, 2022). "IFITM1 affects the levels of pAkt, pSTAT3, SOX2, MYC and p-β-catenin, which are linked to cancer stem cell regulation." (PMID 36466909, 2022). "On the other hand, in vitro studies often describe that targeted IFITM1, IFITM2 and IFITM3 protein silencing in cancer cells causes proliferation inhibition, cell cycle arrest and senescence." (PMID 36466909, 2022). "This is consistent with our previous research wherein we found a translational role for the IFITM family in the context of cancer; the deletion of IFITM1/3 genes suppresses the expression of a subset of proteins for which synthesis is mediated by IFNγ." (PMID 36008984, 2022). "We investigate new protein–protein interactions for IFITM1/3 in the context of cancer that would shed some light on how IFITM1/3 attenuate the expression of targeted proteins such as HLA-B." (PMID 36008984, 2022). "Next, we investigated IFITM1 protein levels in primary lung tumor tissues from patients with SCLC using a commercially available cancer tissue array (CTA)." (PMID 32668617, 2020). "IFITM1 is involved in several types of cancers, e.g. it promotes the aggressiveness of colorectal cancer cells." (PMID 29051711, 2017). "We found that the mRNA expression level of the interferon-induced transmembrane gene (IFITM1) is reduced in cancer tissues." (PMID 29051711, 2017). "Control or IFITM1 shRNA-transduced cancer cells including SW620, HCT116 and HT29 were incubated for 72 hours to determine proliferation in vitro." (PMID 27852071, 2016). "SW620 cancer cells were transiently transfected with either control vector or IFITM1 expression construct (IFITM1 OE) and IFITM1 expression was confirmed by RT-qPCR and immunoblot." (PMID 27852071, 2016). "Interferon-induced transmembrane protein 1 (IFITM1) is also overexpressed in various cancers." (PMID 42286874, 2026).
cancer (continued). "Following the analysis of the data obtained from MS, the effects of the IFITM1 protein were further validated by performing functional assays focused on cancer cell adhesion, migration, invasion and sphere formation-processes driven by changes in surfaceome composition." (PMID 40314078, 2025). "Therefore, IFITM1 upregulated by p-FoxM1S25 should be important to regulate cancer metastasis and TAM polarization in the TME." (PMID 37968723, 2023). "We assessed the prognostic value of IFITM1 in multiple types of cancer." (PMID 36591519, 2022). "Although we focused on the role of IFITM1/3 in regulating HLA-B, there may be other cancer- and virus-originated proteins for which expression may be mediated by IFITM1/3." (PMID 36008984, 2022). "Among these members, the role of IFITM3 in cancer is becoming apparent similarly as IFITM1." (PMID 32668617, 2020). "We performed a sphere-formation assay to determine whether IFITM1 contributed to the capacity of cancer cells to proliferate and self-renew." (PMID 31781559, 2019). "The reason why IFITM1 showed various effects in different types of cancer remains unknown, and further studies are needed." (PMID 29051711, 2017). "However, the functional significance and signaling mechanism of IFITM1 in the progression of various cancers remain unanswered." (PMID 27852071, 2016). "Here, we ectopically expressed IFITM1 in cancer cells to examine whether IFITM1 could promote proliferation and migration of cancer cells." (PMID 27852071, 2016). "Also, IFITM1 depletion resulted in a significant reduction in the mobility of cancer cell lines, whereas ectopic expression of IFITM1 promoted the migration of cancer cells." (PMID 27852071, 2016). "As the first identified member of this superfamily, IFITM1 (CD225) has been studied for its involvement in the inhibition of viral replication, promotion of cancer cell invasion, and expression in transformed cells as a cancer marker." (PMID 20847954, 2010). "Similarly, previous studies have shown high expressed IFITM1 in a variety of cancers." (PMID 33869009, 2021). "To explore the effects of miR-147a in the mechanisms and functions of LINC00847, we next sought to discover the downstream target of miR-147a using starbase algorithm, and found that IFITM1, a well-known oncogene in diverse cancer types, might be the possible target." (PMID 33968966, 2021). "However, interactions between cancer and IFITM1 are controversial." (PMID 31781559, 2019). "We also determined whether IFITM1 was required for the invasion of cancer cells in vitro." (PMID 27852071, 2016). "The protein expression of IFITM1, IFITM2, or IFITM3 are predictors for poor prognosis in numerous cancers such as colorectal, prostate, ovarian, lung, liver, breast, and astrocytoma." (PMID 36435199, 2023). "EP3 showed a unique signature of interferon-stimulated genes IFIT1-3 (logFC >2.5), IFITM1-3 (logFC >0.6), and ISG15 (logFC = 2.5), previously characterized as markers of cancer stem cells (CSC)." (PMID 38328306, 2023). "We also found that MUC1-C is necessary for the expression of IFN-stimulated genes (ISGs), including IFIT1/3, OAS1/3, IFITM1, IFI44L and MX1, that promote DNA damage resistance, chronic inflammation and cancer progression." (PMID 34657147, 2022). "To date, IFITM1, IFITM2 and IFITM3 overexpression has been described in various cancer cell lines and tissues." (PMID 36466909, 2022). "Several studies have postulated that high expression of the IFN-stimulated IFITM1 and IFITM3 proteins can stimulate more aggressive growth of human cancers." (PMID 36008984, 2022). "The expression of IFITM1 is induced by IFN-α and/or IFN-γ (to a lesser extent), and has been reported in several types of cancer cells 39,40." (PMID 32626514, 2020). "Cancer cell lines (SW620, HT29, and HCT116) transduced with either shLacZ or IFITM1 shRNA were seeded on an insert of the transwell system and incubated for 18 hrs to examine migration." (PMID 27852071, 2016).
cancer (continued). "In addition, genes reported to be involved in immunological response to pathogens, such as IL-8, IFITM1, IFITM2, and RHOB were also significantly differentially expressed in cancer tissue." (PMID 38505585, 2024). "In addition to the widely studied antiviral function of the IFITMs, IFITM1 and IFITM3 also function as a pro-oncogenic protein for which the expression has been reported in various cancers such as breast, cervix, colon, leukemia, ovary, brain, and esophagus." (PMID 36008984, 2022). "Moreover, the cancer stem cell markers CD44 and CD133 were shown to be downregulated after IFITM1 depletion." (PMID 36466909, 2022). "MF HSC/MPP showed a high expression of immune and inflammatory pathways (HLA genes, GBP4, and IFITM1), a matrix- and collagen-degrading enzyme (MMP2), and genes with oncogenic function (MYCN, KRT8, and KRT18) that have been correlated with cancer progression and poor survival." (PMID 34525349, 2021). "Mechanically, miR-147a/IFITM1 axis was a downstream target of LINC00847, and silencing of miR-147a could rescue the anti-cancer effects of LINC00847 knockdown on NSCLC cell behaviors." (PMID 33968966, 2021). "Other highly upregulated genes included interferon-induced transmembrane protein 1 (IFITM1), which, together with other interferon-regulated genes, are highly upregulated in several cancers and assigned key roles in driving aggressiveness and chemotherapy resistance." (PMID 32764426, 2020). "Notably, genetic KO of IFITM1 and IFITM3 inhibited the synthesis of a subset of IFN-responsive proteins, which is consistent with the notion of an immunoregulatory role for IFITMs in cancer." (PMID 36435199, 2023). "Moreover, IFITM1 and IFITM3 confer a sphere-forming ability to various cancers." (PMID 36466909, 2022). "The IFITM1, IFITM2 and IFITM3 proteins influence the epithelial–mesenchymal transition (EMT) status, cell migration, invasion and the presence of distant metastases, as has been shown in both in vitro and in vivo studies performed with various cancer cell lines, animal models and patient samples." (PMID 36466909, 2022). "Nonetheless, the molecular mechanism whereby IFITM1 and IFITM3 proteins regulate cancer is not well defined." (PMID 36008984, 2022). "While the potential interaction between IFITM1 and RhoC-GTPase was not directly assessed in our study, it has been reported that Rho-GTPases can interact with caveolin 1 (CAV-1) in cancer cells." (PMID 26897526, 2016). "Compared to uninfected cancers, the infected cancers had significant upregulation of nine cellular factors (FCER2, MS4A1 (CD20), PLUNC, TNFSF9, TRAF1, CXCL11, IFITM1, PPARG, and FCRL3), implying that EBV is not an innocent bystander with respect to biochemical impact." (PMID 22929309, 2012).
inflammation (2 papers, 2021 to 2023). Aberrant reaction of the microcirculation characterized by movement of fluid and leukocytes from the blood into extravascular tissues. "For example, a recent study suggested that the classical monocytes overexpress interferon-induced transmembrane protein 1 in perinatal hepatic inflammation, which is a highly specific immune marker of normal endometrial stroma." (PMID 37223018, 2023). "In line with results from the RV‐induced airway inflammation model, increased mRNA expression of Cxcl1, Cxcl2, and Ifitm1 in HDM‐stimulated Mir146a/b−/− splenocytes was detected." (PMID 34185416, 2021).
benign tumor (1 paper, 2024). "In our previous study, based on reverse transcription–polymerase chain reaction (RT-PCR)-based differential display analysis, we found that interferon-induced transmembrane protein 1 (IFITM1) was downregulated in MPNST tissues of patients with NF1 compared to that in benign tumor tissues." (PMID 39273214, 2024).
respiratory disease (1 paper, 2021). "For example, Echinaforce® treatment increases expression IFI27 and IFITM1, which both play critical roles in antiviral immunity and disease severity in respiratory disease." (PMID 33980308, 2021).
IFITM1 also shares sentences with these, for which no sentence is quoted: adenocarcinoma (3 papers); chronic myeloid leukemia (3); schizophrenia (3); autoimmune thyroid disease (2); breast tumors (2); colon adenocarcinoma (2); leukaemia (2); lymphoma (2); oral cancer (2); primary immunodeficiency (2); small cell lung carcinoma (2); ulcerative colitis (2); acral melanoma (1); acute myeloid leukemia (1); Alzheimer disease (1); Arthritis (1); bacterial pneumonia (1); Barrett esophagus (1); chronic cervicitis (1); chronic hepatitis B (1); ciliopathies (1); colorectal adenocarcinoma (1); cutaneous melanoma (1); dermatomyositis (1); diffuse astrocytoma (1); dilated cardiomyopathy (1); embryonal carcinoma (1); encephalitis (1); endometrial cancer (1); gouty arthritis (1).
A further 25 diseases each share a sentence with IFITM1 in 1 paper.